MIR211 (microRNA 211)
Synonyms: hsa-mir-211; MIRN211; mir-211
Gene: MicroRNA gene on chromosome 15 (31,065,032 to 31,065,141, reverse strand). Ensembl gene ENSG00000207702.
Pathways (Reactome):
Developmental Biology: Regulation of MITF-M-dependent genes involved in apoptosis
Gene Ontology:
Cellular component: RISC complex
Homologues: Orthologues: chimpanzee ptr-mir-211 (100% identical), macaque mml-mir-211 (96% identical), dog MIR211 (79% identical), rat Mir211 (74% identical), guinea pig MIR211 (72% identical), zebrafish dre-mir-204-2 (57% identical). Paralogues in human: MIR204 (61% identical).
Diseases named in the same sentence as MIR211 in open-access papers:
MIR211 is named in the same sentence as 12 diseases in open-access papers, as found by Europe PMC text mining. Sharing a sentence is not in itself a finding about the gene and the disease. The quoted sentences say what the papers report.
Arthritis (1 paper, 2022). Inflammation of a joint. "Structure-specific recognition protein 1 (Ssrp1) knockdown exerts anti-arthritis effect in collagen-induced arthritis (CIA) Mir204/Mir211 double knockout (dKO) mice." (PMID 36511897, 2022). "Compared with WT mice with CIA induction, Mir204/Mir211 dKO mice with CIA induction showed much more severe paw swelling and increased arthritis score." (PMID 36511897, 2022).
cataract (1 paper, 2024). Partial or complete opacity of the crystalline lens of one or both eyes that decreases visual acuity and eventually results in blindness. "We note that hyper-mature cataracts have been reported in Mir204; Mir211-dKO mice at 10–15 months of age." (PMID 38334649, 2024).
epithelial ovarian cancer (1 paper, 2020). "In epithelial ovarian cancer (EOC) cells, MIR211 expression was down-regulated and increased the expression of cyclin D1 and CDK1 and thereby apoptosis." (PMID 33628737, 2020). "A recent report suggests that MIR211 can target PHF19 and thereby inhibit cell proliferation, migration and apoptosis in ovarian cancer." (PMID 33628737, 2020).
gastric cancer (1 paper, 2020). A primary or metastatic malignant neoplasm involving the stomach. "In gastric cancer cells, overexpression of MIR211 directly inhibits SOX4 expression and thereby down regulates tumor metastasis, suggesting the involvement of cancer stem cells." (PMID 33628737, 2020). "MIR211 regulates Matrix metalloproteinase-9 (MMP-9) and thereby reduces EMT in gastric cancer." (PMID 33628737, 2020).
head and neck squamous cell carcinoma (1 paper, 2020). A squamous cell carcinoma that arises from any of the following anatomic sites: lip and oral cavity, nasal cavity, paranasal sinuses, pharynx, larynx, and salivary glands. "Increased expression of MIR211 in head and neck squamous cell carcinoma (HNSCC) inhibited TGFβRII and thus decreased the SMAD3 phosphorylation and increased c-myc expression." (PMID 33628737, 2020).
melanoma (1 paper, 2020). A malignant, usually aggressive tumor composed of atypical, neoplastic melanocytes. "BRN2 (Brain-Specific Homeobox/POU Domain Protein class 3 transcription Factor 2 or POU3F2), a transcription factor, is associated with aggressive melanoma development, and MIR211 is a strong suppressor of BRN2 mediated invasiveness." (PMID 33628737, 2020). "For example, up-regulation of MIR211 expression down-regulates Warburg effect in melanoma tumor cells associated with an inhibition of the growth of human melanoma cells in vitro, and yet these conditions robustly increase tumor growth in xenografted mice." (PMID 33628737, 2020). "MIR211 contributes to melanoma progression not only by targeting genes of melanoma cells but also by modulating the tumor niche in melanoma microenvironment via communication through melanosomes." (PMID 33628737, 2020). "Melanosomal-MIR211 released from melanoma cells are transferred into the surrounding primary skin fibroblasts and which then induce their reprogramming into cancer-associated fibroblasts (CAFs) by targeting the IGF2R mRNA and through regulating MAPK signaling." (PMID 33628737, 2020). "It was recently shown that adipocytes secret IL6, which leads to downregulation of MIR211 in melanoma which further promotes melanoma invasion." (PMID 33628737, 2020). "In melanoma cells, MIR211 can modulate EMT by targeting RAB22A, a member of the RAB family of small GTPase, which regulates tumor invasion and metastasis in various cancer types." (PMID 33628737, 2020). "Bcl-2, a pro-apoptotic protein, regulates the expression of MIR211 by modulating MITF expression in melanoma cell lines, in addition to the reciprocal regulation of BCL2 by MITF." (PMID 33628737, 2020). "Paradoxically, when MIR211 expression was artificially induced in human melanoma cell lines, where its expression is generally reduced relative to those in melanocytes, which were xenografted into immunodeficient mice they resulted into aggressive tumor growth." (PMID 33628737, 2020). "Conversely, when MIR211 levels were increased artificially in melanoma cells, a significant inhibition of growth and in vitro invasive properties were observed, which could again be reversed by inhibiting MIR211 by an antagomir, fulfilling the criteria for a tumor-suppressor molecule." (PMID 33628737, 2020). "Thus, the EZH2/DNMT1/MIR211/RAB22A axis might provide novel insights into the molecular pathogenesis of both melanoma and glioblastoma, particularly on the EMT processes in these two different cancers." (PMID 33628737, 2020). "Decreased MIR211 levels were correlated with increased cell proliferation and Epithelial to Mesenchymal Transition (EMT, a morphogenetic state transition that is important for the development of numerous cancer types) of melanoma cells." (PMID 33628737, 2020). "In summary, MIR211 and its paralog MIR204 together regulate a number of genes whose expression are related to both tumor suppressor and oncogenic activities in a number of different cancer types including melanoma." (PMID 33628737, 2020).
cancer (1 paper, 2020). A tumor composed of atypical neoplastic, often pleomorphic cells that invade other tissues. "Apart from regulating the apoptosis, Endoplasmic reticulum stress and EMT, MIR211 also regulates various other processes important for cancer, including angiogenesis, through influencing multiple signaling pathways." (PMID 33628737, 2020). "MIR211 acts as a tumor suppressor in a variety of cancer types, it can also act as an oncogenic regulator in others." (PMID 33628737, 2020). "Summary of MIR211 target genes and their roles in various cancer types." (PMID 33628737, 2020).
genetic disorder (1 paper, 2021). "The 15q13.3 microdeletion syndrome is a genetic disorder characterized by a wide spectrum of psychiatric disorders that is caused by the deletion of a region containing 7 genes on chromosome 15 (MTMR10, FAN1, TRPM1, MIR211, KLF13, OTUD7A, and CHRNA7)." (PMID 33785025, 2021).
tumor (1 paper, 2020). "Deletion of MIR211 gene in these xenografted cells produced much reduced tumors, supporting the conclusion that this MIR211 was directly responsible for the hypertrophic tumor phenotype." (PMID 33628737, 2020). "This proposal is also consistent with the tumor suppressor role of MITF as a directly activating transcription factor of MIR211 gene." (PMID 33628737, 2020). "Previous studies suggested that in certain tumors MIR211 acts as a tumor suppressor while in others it behaves as an oncogenic regulator." (PMID 33628737, 2020). "These evidences together are consistent with the proposal that MIR211 exerts its tumor suppressor properties by means of direct negative regulation of potentially oncogenic mRNAs." (PMID 33628737, 2020). "By targeting SNAI1 mRNA, MIR211 directly regulates the metastatic behavior of tumor cells in renal cancer cells." (PMID 33628737, 2020). "Indeed, separate sets of target genes of MIR211 have been shown to be responsible for its tumor-enhancing role." (PMID 33628737, 2020).
MIR211 also shares sentences with these, for which no sentence is quoted: inflammation (1 paper); psychiatric disorder (1); rheumatoid arthritis (1).